SOX9 (SRY-box transcription factor 9)
Diseases named in the same sentence as SOX9 in open-access papers (continued):
Sharing a sentence is not in itself a finding about the gene and the disease.
cystic hygroma (2 papers, 2022 to 2024). A benign lymphatic neoplasm usually arising from the neck and characterized by cystic dilation of the lymphatic vessels. "Although with the development of next-generation sequencing technology, genetic variants such as SOX9, KDR, and BRCA1 are involved in the pathogenesis of cystic hygroma, the specific pathogenesis of cystic hygroma remains unclear." (PMID 38650036, 2024).
deafness (2 papers, 2023 to 2025). An inherited or acquired condition characterized by the complete loss of the ability to hear from one or both ears. "It was shown that SOX9 causes deafness via distinct mechanisms in the endolymphatic sac (ES)/duct and cochlea." (PMID 40109362, 2025). "In a recent study, it was observed that heterozygous mice carrying the Y440X mutation in the Sox9 gene, which results in the truncation of the C-terminal transactivation domain of Sox9, exhibited neurosensory deafness." (PMID 37681879, 2023). "Thus, manipulating Sox9 expression or activity may be an important pathway when designing therapies to treat deafness caused by loss or dysfunction of HCs and/or SCs." (PMID 37681879, 2023).
dyslipidemia (2 papers, 2019 to 2025). "In this study, we observed that ASCs affected by metabolic syndrome exhibited a significant reduction in their chondrogenic potency as characterized by a collapse of the Sox9 gene transcription and a consequent downregulation of the related cartilaginous factors." (PMID 31847882, 2019).
germ cell tumor (2 papers, 2012 to 2019). A benign or malignant, gonadal or extragonadal neoplasm that originates from germ cells. "FN1, AXL, and SOX9 demonstrated a similar pattern of expression across all lines and have been shown by others to be over expressed in germ cell tumors." (PMID 22737227, 2012). "Gonadal biopsy and immunohistochemical biomarkers (OCT3/4 (POU5F1), TSPY, SOX9, FOXL2 and KITLG (SCF)) are important to characterize situations in which GCC development is possible (germ cells tumors)." (PMID 31721911, 2019).
Glomerular sclerosis (2 papers, 2022). Accumulation of scar tissue within the glomerulus. "In conclusion, JQ1 reduced experimental glomerulosclerosis by inhibiting SOX9/COLIV." (PMID 36613933, 2022). "Our results demonstrated that JQ1 inhibited SOX9/COLIV, to reduce experimental glomerulosclerosis, supporting further research of iBET as a potential therapeutic option in progressive glomerulosclerosis." (PMID 36613933, 2022).
gonadal dysgenesis (2 papers, 2008 to 2012). A congenital disorder characterized by the presence of extremely hypoplastic gonads preventing the development of secondary sex characteristics. "Given that it has been estimated that up to 70% of such cases of gonadal dysgenesis in the human population remain unaccounted for by mutations in known sex determining genes such as SRY and SOX9, such a gene-driven approach to identifying candidates is well motivated." (PMID 19116663, 2008).
gonadoblastoma (2 papers, 2015 to 2018). A mixed germ cell/sex cord-stromal tumor characterized by the presence of large germ cells which resemble seminoma cells and small cells which resemble Sertoli or granulosa cells. "Risk of gonadoblastoma is high when the early stage of Sertoli cell differentiation is disrupted by mutations in SRY, WT1, SOX9, DMRT1, FOG2/GATA4, FGF9 etc.." (PMID 28825592, 2018). "As for gonadoblastoma, co-expression of SOX9 and FOXL2 was observed only in a minority of sex cord cells with 45,X." (PMID 25860218, 2015). "Unexpectedly, our case showed co-expression of SOX9 and FOXL2 in abnormally shaped seminiferous tubules and gonadoblastomas." (PMID 25860218, 2015).
granulosa cell tumor (2 papers, 2016 to 2021). A slow-growing, malignant tumor, characterize by the presence of granulosa-like cells and Call-Exner bodies, that is almost always found in the ovary. "had performed immunohistochemical expression of SOX9 through the regulation of prostaglandin D Synthase (Pdgs) in four primary SCST samples, including two Sertoli-Leydig cell tumors (one well-differentiated and one poorly differentiated) and two granulosa-cell tumors." (PMID 34881182, 2021). "Because granulosa cells may transdifferentiate into Sertoli cells in granulosa cell tumors, we assessed whether there were Sertoli cell-like components in the TGFBR1-CAAcre model by immunofluorescence using an antibody directed to SRY (sex determining region Y)-box 9 (SOX9), a Sertoli cell marker." (PMID 27344183, 2016).
hematoma (2 papers, 2022 to 2023). A hematoma is a collection of blood from a vascular structure into an extravascular space. "In line with this, the expression of osteogenic differentiation markers RUNX2, ALP, BMP4, and Noggin as well as the chondrogenic differentiation marker SOX9 were all significantly lower in smokers’ hematomas (comp." (PMID 35621464, 2022). "Treatment with MBE could not rescue the ALP activity of the smoker in vitro facture hematomas and showed a slight trend in inducing RUNX2 and SOX9 expression." (PMID 37569229, 2023).
Hypertension (2 papers, 2019 to 2020). The presence of chronic increased pressure in the systemic arterial system. "Thus, we suggest the SOX9-miR-202-3p-sST2 signaling axis might be critical for the development of hypertension complicated by hyperuricemia and hyperhomocysteinemia and our study will focus on it in next step." (PMID 32338289, 2020).
hyperthyroidism (2 papers, 2022 to 2023). Overactivity of the thyroid gland resulting in overproduction of thyroid hormone and increased metabolic rate. "This issue needs to be further studied, because initially we expected that there would be a reduction in Sox9 caused by maternal hyperthyroidism." (PMID 35448479, 2022). "Accordingly, we postulated that the increased Sox9 expression caused by maternal hyperthyroidism could be related to decreased VEGF expression in growth plates." (PMID 35448479, 2022). "In the present study, cultures of chondrocytes derived from the femoral epiphysis of neonates subjected to maternal hyperthyroidism showed increased Sox9 expression." (PMID 35448479, 2022). "Unlike the other transcripts studied that remained unchanged or decreased, Sox9 was the only one that increased in chondrocytes extracted from neonates exposed to maternal hyperthyroidism." (PMID 35448479, 2022). "At 21 days, the cultures of chondrocytes extracted from newborn rats exposed to maternal hyperthyroidism revealed a significant decrease in the expression of the Col2 and Acan gene transcripts, along with the increased expression of Sox9, when compared with the control group." (PMID 35448479, 2022). "However, the relationship between Sox9 and Vegf in the cartilage growth of animals with IUGR induced by maternal hyperthyroidism needs to be elucidated." (PMID 35448479, 2022). "Maternal hyperthyroidism did not alter the chondrocyte morphology, but significantly reduced the percentage of PAS+ areas, decreased the expression of the gene transcripts of Col2 and Acan, and increased Sox9 expression." (PMID 35448479, 2022).
keloid (2 papers, 2021 to 2022). An irregularly shaped, elevated mark on the skin caused by deposits of excessive amounts of collagen during wound healing. "The results showed that the expression of 12 genes (Hub genes) significantly increased in the development of keloid (P < 0.05) while that of TGFB3, SOX9, and BGN did not change significantly (P > 0.05)." (PMID 35872873, 2022).
kidney damage (2 papers, 2022 to 2023). "As the previous experiments reported, mice with surgery demonstrated severe kidney damage, and the activation of SOX9+ RECs started within 24 h post injury." (PMID 36601693, 2023).
mesenchymal chondrosarcoma (2 papers, 2019 to 2023). A morphologic variant of chondrosarcoma arising from bone and soft tissue. "In support of this idea, Sox9 expression was maintained upon HEY1::NCOA2 introduction throughout the carcinogenic process of mesenchymal chondrosarcoma, as Sox9 is expressed at high level in eSZ cells." (PMID 37212282, 2023).
metastatic cancer (2 papers, 2021 to 2024). A carcinoma which has spread from the original site of growth to another anatomic site. "In particular, co-mutations of APC with TCF7L2 or SOX9 may identify a subgroup of metastatic cancers with favorable prognosis." (PMID 39587554, 2024). "Additionally, in previous study, Cldn7 expression was significantly lower in metastatic cancer tissues than in primary tumours, while Sox9 expression was increased in liver metastasis and lung metastasis cancer tissues." (PMID 34281572, 2021).
metastatic tumors (2 papers, 2015 to 2018). "Furthermore, we detected the protein expression of SOX9, COL10A1, Ki-67 (cell proliferation marker), CD31 and CD34 (angiogenesis markers) in peritoneal metastatic tumors of GC patients." (PMID 30154451, 2018). "We interrogated if SOX9 has a role in overall patient survival in all patients regardless of primary or metastatic disease." (PMID 25885555, 2015). "The IHC assay of lung metastatic tumors revealed that knockdown of COL10A1 enhanced the expression of E-cadherin (epithelial marker) and decreased the expression of Vimentin (mesenchymal marker), while there was not significant decrease in SOX9 expression." (PMID 30154451, 2018).
microphthalmia (2 papers, 2007 to 2024). Congenital or developmental anomaly in which the eyeballs are abnormally small. "Furthermore, disrupted SOX9 expression in the 'odd sex' transgenic mouse, which results in sex reversal, also causes an eye phenotype with microphthalmia with cataracts." (PMID 17935617, 2007). "SRY-box transcription factor 9 (SOX9) was initially expressed in the lens pit, and Dct-Sox9 transgenic mice reported are accompanied with microphthalmia with cataract." (PMID 38933921, 2024).
multiple myeloma (2 papers, 2022 to 2024). "SERPINE1 (together with ANGPTL4, GDF15, CXCL12, SOX9, HOXB6, and ANK3) was even described as a TA-MSC factor, namely, in mesenchymal stromal cells of the bone marrow that supported myeloma cell growth." (PMID 39011489, 2024).
myopia (2 papers, 2022 to 2025). "In 2012, researchers from Johnson and Johnson Vision Care also recognized specific role of SOX9 for extreme myopia." (PMID 40110040, 2025). "On the one hand, the results of Metascape revealed a potential role of TF in the development of myopia with the enrichment of Smad6, NrOb2, Gtf2i, Tfap2a, Pax7, Pax6, Sox9 and Smad3." (PMID 34841657, 2022).
nasopharyngeal carcinoma (2 papers, 2021 to 2022). A carcinoma arising from the nasopharyngeal epithelium. "Furthermore, in another GEO dataset, GSE135083, the SOX9 expression was also elevated in CDDP-resistant nasopharyngeal carcinoma 5-8F cells (5-8F DDP) compared to CDDP-sensitive 5-8F cells (5-8F) (LogFC = 3.807, p < 0.001)." (PMID 34899911, 2021). "In conclusion, circSOX9 acts as an oncogene in the progression of NPC through miR-485-3p/SOX9, indicating that circSOX9 can be used as a potential therapeutic target and predictive marker for nasopharyngeal carcinoma." (PMID 35700516, 2022).
neurofibroma (2 papers, 2024 to 2025). An intraneural or extraneural neoplasm arising from nerve tissues and neural sheaths. "Another study further found that SOX9 activates collagen VI secretion in neurofibroma through the upregulation of procollagen C-endopeptidase enhancer (PCOLCE)." (PMID 40025071, 2025). "High SOX9 expression correlates with the malignant potential of neurofibroma/MPNST." (PMID 40025071, 2025).
non-Hodgkin lymphoma (2 papers, 2008 to 2020). Distinct from Hodgkin lymphoma both morphologically and biologically, non-Hodgkin lymphoma (NHL) is characterized by the absence of Reed-Sternberg cells, can occur at any age, and usually presents as a localized or generalized lymphadenopathy associated with fever and weight loss. "SOX-9 staining differentiates Chs from various small cells round tumour such as small cell osteosarcomas, non-Hodgkin lymphomas and Ewing/PNET family tumours." (PMID 18673514, 2008).
ovarian tumors (2 papers, 2012 to 2021). "Therefore, the significance of the expression and function of SOX9 in ovarian tumors remains unclear." (PMID 34881182, 2021).
Parkinson disease (2 papers, 2020 to 2024). A progressive degenerative disorder of the central nervous system characterized by loss of dopamine producing neurons in the substantia nigra and the presence of Lewy bodies in the substantia nigra and locus coeruleus. "Similarly to our research, in Parkinson’s disease, deficiency of miR-124-3p delivery to the subventricular zone impairs neurogenesis and neural cell differentiation due to reduction of silencing the target cell-fate proteins Sox9 and Jagged1." (PMID 32984332, 2020).
postmenopausal osteoporosis (2 papers, 2022). Metabolic disorder associated with fractures of the femoral neck, vertebrae, and distal forearm. "While the COL9A1 promoter region can be transactivated by SOX9, rs73354570 of SOX9 has been significantly associated with postmenopausal osteoporosis." (PMID 35163424, 2022). "COL9A1 and SOX9 are related to the genetic susceptibility of postmenopausal osteoporosis." (PMID 35198553, 2022).
prostate adenocarcinoma (2 papers, 2023 to 2024). "Recently, a new mechanism for regulating the development of prostate adenocarcinoma (PCa), which involves the deregulation of SOX9, HMGB3, and NANOG, was discovered." (PMID 39062899, 2024). "Thus, HMGB3/SOX9-mediated NANOG induction may lead to increased viability of prostate adenocarcinoma cells." (PMID 39062899, 2024). "HMGB3 cooperates with SOX9 to induce NANOG transactivation, promote the expression of oncogenic genes downstream of NANOG, and further enhance prostate adenocarcinoma cell survival and migration." (PMID 37328851, 2023).
prostate intraepithelial neoplasia (2 papers, 2013 to 2017). A neoplastic proliferation of the epithelial cells that line the acini and the ducts of the prostate gland. "Apart from loss of Nkx3.1 a decrease in Pten specifically in the prostate, sustained androgen receptor expression, increased Myc and Sox9 also promote early stages prostatic intraepithelial neoplasia." (PMID 23786676, 2013).
retinoblastoma (2 papers, 2021 to 2022). A malignant tumor that originates in the nuclear layer of the retina. "In retinoblastoma, LINC00152 is activated by SP1 to inhibit miR-30d and thus regulate the expression of SOX9 and ZEB2 to promote tumor recurrence." (PMID 36033524, 2022).
rheumatoid arthritis (2 papers, 2024 to 2025). A chronic, systemic autoimmune disorder characterized by inflammation in the synovial membranes and articular surfaces. "SOX9 is also implicated in chronic inflammatory and autoimmune disorders such as rheumatoid arthritis (RA), inflammatory bowel disease (IBD), and Sjögren’s syndrome." (PMID 41293317, 2025). "Furthermore, alterations in SOX9 expression have been observed in joint synovial cells in the context of rheumatoid arthritis (RA), where abnormal proliferation and inflammatory responses of these cells are characteristic features of the disease." (PMID 41293317, 2025).
schizophrenia (2 papers, 2016 to 2025). A major psychotic disorder characterized by abnormalities in the perception or expression of reality. "Astrocytes differentiate via nuclear factor I-A, Sox9, and Notch pathways, occurring within a neuronal environment that may already be compromised in the early stages due to the genetic factors associated with the ‘two-hits’ model of schizophrenia." (PMID 40427508, 2025). "There are 4 genes, SOX9, HEPH, AQP1, and SDC3 as susceptible genes, and it was already reported that SDC3 has a weak association with schizophrenia in related GWAS." (PMID 27510319, 2016).
soft tissue sarcoma (2 papers, 2021 to 2025). A malignant neoplasm arising from muscle tissue, adipose tissue, blood vessels, fibrous tissue, or other supportive tissues excluding the bones. "In agreement with previous reports, our data expand on earlier evidence of SOX9, GATA3, and GATA4 dysregulation in soft tissue sarcomas." (PMID 41303462, 2025).
steatosis (2 papers, 2019 to 2021). Increased lipid within the cytoplasm of cells. "Alb-Pten mice developed severe steatosis throughout the entire liver, whereas Sox9-Pten mice only displayed mild lipid accumulation in the focal areas surrounding the tumors." (PMID 34083580, 2021). "With the presence of steatosis or chemical induced injury, SOX9+ cells accumulate in the liver, resulting in a remarkably increased incidence and early onset of liver tumors, all originating from transformed SOX9+ cells." (PMID 34083580, 2021). "Overall, these results indicate that steatosis sends hyperplastic signals to SOX9+ cholangiocytes and periportal hepatocytes." (PMID 34083580, 2021). "Using the Sox9-Pten mice, our study here shows that the genotoxic event occurring in the putative SOX9+ TICs is propagated by steatosis induced by HFD feeding." (PMID 34083580, 2021). "The number of SOX9‐positive hepatocytes was significantly higher in ALI patients than in the simple steatosis patients (P = 0.0121)." (PMID 31651102, 2019). "In addition, we show that steatosis, a common chronic liver condition promotes the formation of tumors from these SOX9+ cells." (PMID 34083580, 2021). "Thus, we tested whether inducing steatosis would promote liver tumorigenesis in the Sox9-Pten mice by feeding the mice HFD." (PMID 34083580, 2021). "Consistent with this role of steatosis, the size of tumors formed in HFD fed Sox9-Pten mice positively correlated with the magnitude of steatosis present in the liver." (PMID 34083580, 2021). "Therefore, we used a liver biopsy specimen of a patient with simple steatosis, which is assumed to have neither bile ducts nor proliferating SOX9‐positive hepatocytes, as a control." (PMID 31651102, 2019).
Swyer syndrome (2 papers, 2012 to 2025). "Swyer syndrome may be caused by SRY mutation (10%–15%), FTHL17, STARD8, SOX9, MAP3K1, NR5A1, and desert hedgehog gene (DHH) mutation as well as other unidentified genes." (PMID 41163677, 2025).
Talipes equinovarus (2 papers, 2020 to 2023). Talipes equinovarus (also called clubfoot) typically has four main components: inversion and adduction of the forefoot; inversion of the heel and hindfoot; equinus (limitation of extension) of the ankle and subtalar joint; and internal rotation of the leg. "Interestingly, bilateral talipes equinovarus after birth was also observed in case 42 who was ultimately classified as having a VUS of the SOX9 gene mutation." (PMID 38318287, 2023).
thymic carcinoma (2 papers, 2021 to 2022). Thymic carcinoma (TC) is a type of thymic epithelial neoplasm characterized by a high malignant potential. "In addition, SOX9 was also highly expressed in thymic carcinoma." (PMID 34778027, 2021). "In addition, SOX9 expression was positively associated with the expressions of TRPM5, which is required for the function of thymic tuft cells, and KIT, which is frequently expressed in thymic carcinomas." (PMID 34778027, 2021).
thyroid (2 papers, 2022 to 2025). "Other genes implicated in syndromic CDH include NK2 homeobox 1 (NKX2-1), which is associated with thyroid dysgenesis and respiratory issues, and SRY-box transcription factor 9 (SOX9), which is involved in sex determination and cartilage formation." (PMID 40710310, 2025). "Likewise, the discovery that TSH finely regulates Sox9 might indicate a role for this transcription factor in chronically challenging thyroid states, such as hypo- and hyper-thyroidism." (PMID 35140269, 2022).
ulcerative colitis (2 papers, 2020 to 2024). An inflammatory bowel disease involving the mucosal surface of the large intestine and rectum. "Examples include, SOX9, an important regulator of cell proliferation in the intestinal epithelium and PDE4D, which is known to be associated with ulcerative colitis." (PMID 33308304, 2020).